ALB (albumin)
Diseases named in the same sentence as ALB in open-access papers (continued):
Sharing a sentence is not in itself a finding about the gene and the disease.
membranous nephropathy (31 papers, 2013 to 2025). "In the cohort, on which the GN-risk-score is based, the frequency of TE in NS due to membranous glomerulonephritis and a serum albumin < 20 g/L was 11%." (PMID 36064370, 2022). "Overall, our data does not contradict current international guidelines from KDIGO, where PAC is suggested for NS patients with low risk of bleeding and S-albumin <20–25g/L, especially for patients with membranous nephropathy." (PMID 34319998, 2021). "In the current study, we attempted to investigate its renoprotective activity and underlying mechanisms in a rat model of membranous glomerulonephritis induced by cationic bovine serum albumin (c-BSA)." (PMID 23990847, 2013). "The KDIGO (Kidney Disease Improving Global Outcomes) guidelines for glomerulonephritis from 2012 suggest use of prophylactic warfarin in NS patients with high risk of VTE, especially patients with membranous nephropathy, with serum albumin <20–25g/L who also have a low risk of bleeding." (PMID 34319998, 2021). "Our previous basic studies have also shown that Sanqi formula could effectively help rat model of membranous nephropathy via reducing proteinuria, increasing serum albumin, ameliorating renal damage which is associated with the suppression of nuclear factor-kappa B (NF-κB)." (PMID 37106336, 2023). "Dogs with membranous glomerulonephropathy had lower serum albumin concentrations than other dogs with proteinuric kidney disease in our study." (PMID 40692207, 2025). "Basic endothelin 1 levels correlated negatively with albumin at many monitoring time points in the membranous nephropathy group." (PMID 41517469, 2025). "Research indicates that Lactobacillus can decrease the urinary total protein, urinary protein/creatinine (P/C) ratio, and urine albumin excretion rate, and improve membranous nephropathy by inhibiting the aryl hydrocarbon receptor pathway." (PMID 39861454, 2025). "It have found that Cordyceps sinensis significantly reduces 24-h urinary protein, blood urea nitrogen, serum creatinine levels, and inflammatory markers in rats with membranous glomerulonephritis while increasing serum albumin and total serum protein levels." (PMID 38645562, 2024). "A significant inverse correlation between AT1R antibodies and albumin level in the membranous nephropathy group, r = − 0.51 (p ≤ 0.05), was found." (PMID 36152104, 2022). "Albumin level in the lupus nephritis group was higher compared to membranous nephropathy group and lower compared to c-ANCA vasculitis group." (PMID 36152104, 2022). "An inverse statistically significant correlation between AT1R antibodies and serum albumin (r = − 0.51) in membranous nephropathy group was also found." (PMID 36152104, 2022). "A Chinese fecal microbiome study comparing IgAN patients, membranous nephropathy patients, and healthy controls noted a positive correlation between Prevotella and a higher serum albumin level." (PMID 34078780, 2021). "Via modulation of NF-κB, Cordyceps militaris fruit body extracts ameliorate cationic bovine serum albumin-induced membranous glomerulonephritis by attenuating oxidative stress and renal inflammation." (PMID 27200371, 2016). "In this study, we treated SD rats with cationic bovine serum albumin (C-BSA) to create an animal model of membranous glomerulonephritis and investigated the therapeutic effect of skimmin in protecting against renal injury in this model." (PMID 23990847, 2013). "Thus, prophylactic anticoagulation is recommended to patient with plasma-albumin below 24 g/L if membranous nephropathy and below 20 g/L in other conditions." (PMID 36064370, 2022). "AT1R antibodies are inversely correlated with serum albumin during membranous nephropathy." (PMID 36152104, 2022). "The current scientific literature suggests that patients with low serum albumin levels and membranous nephropathy may benefit from primary prophylactic anticoagulation." (PMID 24829800, 2014).
membranous nephropathy (continued). "The endpoints were sparsely including the serum albumin levels, 24-h urine protein and the remission rate in our study, but they are 3 important index during the treatment of membranous nephropathy, which are used to reflect the severity of membranous nephropathy." (PMID 31791262, 2019). "Patients with IRGN and pauci-immune GN had the lowest median estimated glomerular filtration rate (eGFR) at the time of biopsy, whereas patients with membranous nephropathy and focal segmental glomerulosclerosis (FSGS) had the highest median urine albumin-to-creatinine ratio (ACR)." (PMID 37342151, 2023). "Nevertheless, an inverse correlation between AT1R antibodies and serum albumin levels in membranous nephropathy indicates that despite low values, AT1R antibodies may have some clinical significance even in the early stage of membranous glomerulonephritis." (PMID 36152104, 2022). "Unlike other immune complex-mediated glomerular nephropathy, such as membranous nephropathy, both IgG and albumin showed linear deposition but without dense deposits along GBM and TBM, and complements were negative." (PMID 35953864, 2022). "Our research showed that treatment with skimmin significantly reduced the levels of blood urea nitrogen (BUN), urinary albumin excretion (UAE), and serum creatinine (Scr) as compared with model control after experimental induction of membranous glomerulonephritis (P < 0.01)." (PMID 23990847, 2013).
hypertriglyceridemia (30 papers, 2010 to 2025). A laboratory test result indicating elevated triglyceride concentration in the blood. "Studies have been shown that a deficiency in ALB disrupts intravascular lipolysis, resulting in a shortage of free fatty acids and a diminished clearance of triglyceride, consequently leading to hypertriglyceridemia." (PMID 38628642, 2024). "Finally, CT was negatively associated with male sex, hypertriglyceridaemia, albumin levels, and PLT/haematocrit levels." (PMID 38074505, 2024). "Hypertriglyceridemia was associated with younger age, lower eGFR, shorter duration of CKD, higher body mass index (BMI-SDS), lower serum albumin, and higher diastolic blood pressure." (PMID 38720111, 2024). "Even though there were not any statistical difference of mean value of pre-albumin, phosphorus and triglyceride, the tendency of low pre-albumin, hypophosphatemia and hypertriglyceridemia were recorded." (PMID 37049600, 2023). "In addition to body weight, a cross-sectional study in China has also shown that hypertriglyceridemia is correlated with increased urinary albumin-to-creatinine ratios (ACR)." (PMID 36310191, 2023). "Univariate analysis showed that T2DM, HCV-MASLD, hypertriglyceridemia, hypo-HDL cholesterolemia, AST, ALT, ɤ-GTP, albumin, platelet count, FSG, HDL-C, AFP, LSM, FIB-4 index, aMAP score, and FAST score were significantly associated with HCC development." (PMID 40624408, 2025). "We propose that the lack of albumin diminishes intravascular lipolysis which reduces the plasma triglyceride removal rate and explain both NAR hypertriglyceridemia and FFA deficiency." (PMID 21187011, 2010).
small cell lung carcinoma (30 papers, 2015 to 2026). Small cell lung cancer (SCLC) is a highly aggressive malignant neoplasm, accounting for 10-15% of lung cancer cases, characterized byrapid growth, and early metastasis. "Based on these findings, we hypothesize the patient may have a compound small cell lung cancer and propose the addition of albumin-bound paclitaxel to the treatment regimen." (PMID 40904497, 2025). "Specifically, higher albumin levels were associated with a reduced risk of adenocarcinoma, while elevated MUFA and lactate levels were linked to an increased risk of squamous cell carcinoma and small cell lung cancers, respectively." (PMID 40719999, 2025). "The combination of CBP with Abraxane (Nanoparticle Albumin-Bound Paclitaxel) to treat small cell lung cancer significantly improved the efficacy, reduced the dosing frequency, and removed the requirement for weekly therapy as it showed anticancer activity in patients when it was given every 3 weeks." (PMID 38258094, 2024). "The Glasgow prognostic score (GPS), which is an inflammation‐based index composed of serum levels of C‐reactive protein and albumin, predicts prognosis in patients with small cell lung cancer (SCLC) without ILD." (PMID 33939332, 2021). "Although the mechanisms by which C-reactive protein and albumin support tumor growth are not well known, the high ratio of these proteins in peripheral blood was shown to have a negative prognostic value in small cell lung carcinoma." (PMID 33276524, 2020). "Among albumin-based systems in clinical trials, Aldox (the albumin-binding Dox, also known as INNO-206 or DOXO-EMCH) has been very successful, exhibiting a good profile in a phase 3 study in soft tissue sarcoma and in phase 2 studies in small cell lung cancer, Kaposi’s sarcoma and GBM." (PMID 30405885, 2018).
chronic hepatitis (29 papers, 2012 to 2025). An active inflammatory process affecting the liver for more than six months. "VWF was reported to be associated with the progression of LC in chronic hepatitis and was negatively correlated with platelet count, prothrombin time, and albumin level." (PMID 36002595, 2022). "The TTT value is relatively high even with lower albumin levels associated with chronic hepatitis and chronic inflammation." (PMID 30309341, 2018). "In contrast, chronic hepatitis group showed a significant decrease in total protein and albumin indicating hepatic dysfunction and albumin synthesis is decreased by the liver causing hypoproteinemia." (PMID 29915506, 2018). "The decrease in TP in our population could have a multifactorial etiology: intestinal loss of proteins (both albumin and globulin), reduced albumin and/or globulin synthesis during inflammation or chronic hepatitis." (PMID 36136669, 2022). "Serum BTR and albumin concentration are positively correlated in patients with chronic hepatitis, and similar results were obtained in the athletes of the present study." (PMID 33397493, 2021). "Patients with chronic hepatitis present normal serum albumin levels, as well as low MELD scores and normal sodium concentrations." (PMID 32050594, 2020). "In chronic hepatitis, total protein and albumin were significantly lower than control values with normal ALT, AST, ALP, and gamma-glutamyltransferase values." (PMID 29915506, 2018). "It has been reported that serum albumin and branched-chain amino acids including leucine, isoleucine and valine to tyrosine ratio levels decreased significantly as chronic hepatitis progressed to liver cirrhosis." (PMID 28198443, 2017). "Chronic hepatitis damages the liver and impairs albumin production, as well as HIV." (PMID 40951243, 2025). "Therefore, type-I interferon-mannosylated albumin fusion protein has the potential as a new therapeutic agent for chronic hepatitis." (PMID 38399475, 2024). "This fusion protein exerted excellent hepatoprotective and antifibrotic effects in chronic hepatitis model mice by improving the bioavailability of type-I IFN in Kupffer cells as a result of the high-mannose chains of mannosylated albumin being recognized by the macrophage mannose receptor." (PMID 38399475, 2024). "Therefore, type-I IFN-mannosylated albumin fusion protein has potential as a new therapeutic agent for various types of chronic hepatitis." (PMID 38399475, 2024). "A study reported high plasma AOPPs/ALB ratio in cirrhotic patients with chronic hepatitis C28." (PMID 33093629, 2020). "The liver outcome score comprises serum prognostic markers such as age, sex, albumin, hyaluronic acid and GGT, and was initially established as a predictor of liver-related death in patients with chronic hepatitis C61." (PMID 41271978, 2025). "Recently, aMAP risk score consisting of age, gender, total bilirubin (TB), albumin (ALB), and platelets (PLT) was reported to predict HCC development in patients with chronic hepatitis." (PMID 35218083, 2022). "Inadequate levels of albumin in this patient's laboratory workup have exemplified complications and delays of the healing process, mainly due to her chronic hepatitis diagnosis and lack of maintenance of her healthcare regimen as an undomiciled patient." (PMID 40951243, 2025). "When compared with control and chronic hepatitis groups, HCC patients showed significantly increased ALT, AST, ALP, GGT, total bilirubin, INR, and creatinine levels (p ≤ 0.001) and significantly decreased albumin levels (p<0.001)." (PMID 34452571, 2021). "Moreover, in the chronic hepatitis patients, current smokers were more likely to have lower albumin levels than nonsmokers." (PMID 23075166, 2012).
lupus nephritis (29 papers, 2008 to 2025). Glomerulonephritis in the context of systemic lupus erythematosus. "This cross-sectional study explores the association of non-albumin proteinuria with the severity of tubulointerstitial inflammation in lupus nephritis patients." (PMID 39963635, 2025). "Non-albumin proteinuria is associated with the severity of tubulointerstitial inflammation in lupus nephritis." (PMID 39963635, 2025). "This study concludes that the severity of TI is highly associated with non-albumin proteinuria, as determined by the difference between uPCR and uACR in lupus nephritis." (PMID 39963635, 2025). "Based on univariate analysis, SLE duration at conception, lupus nephritis (LN), history of therapeutic abortion, C3, lupus anticoagulant, IgG, serum ALB, CRP, PRO, HDL, and HCQ levels were significantly associated with the occurrence of fetal loss." (PMID 39044159, 2024). "Furthermore, we also found that deficiency of Ube2m ameliorated lupus nephritis, including lessened total protein and albumin/ creatinine ratio, restored renal structures." (PMID 38221551, 2024). "Further, the albumin content in urine also decreased significantly after treatment with the inhibitor, demonstrating its ability to treat renal impairment associated with lupus nephritis." (PMID 32660060, 2020). "Both anti-PAR 1 and anti-ACE 2 antibody levels correlated positively (in focal and segmental glomerulosclerosis) or negatively (in lupus nephritis) with total protein and albumin at different time points of observation." (PMID 40364208, 2025). "Higher levels of anti-PAR 1 antibodies tend to be connected with lower levels of total protein and albumin in the lupus nephritis group." (PMID 40364208, 2025). "The anti-C3aR baseline serum antibody level correlated negatively with serum albumin level at baseline and after 1 month, 3 months, 12 months, and 2 years of observation in the lupus nephritis group." (PMID 40943842, 2025). "Lupus nephritis, complement 3, immunoglobulin G, serum albumin, C-reactive protein, and hydroxychloroquine were all included in the nomogram model." (PMID 39044159, 2024). "Patients with early nephritis had higher non-renal SLEDAI-2 K and ESR, but lower anti-dsDNA, WBC count and albumin levels compared to those with delayed lupus nephritis." (PMID 32635898, 2020). "Serum SCr, BUN, TC, TG, TP and ALB levels of lupus nephritis mice treated with polysaccharide of large yellow croaker swim bladder (PLYCSB)." (PMID 24667130, 2014). "Additionally, this correlation continues throughout many timepoints, so it seems to support the thesis about the predictive value of anti-C3aR antibodies in terms of total protein and albumin levels in lupus nephritis." (PMID 40943842, 2025). "Therefore, non-albumin proteinuria can be monitored serially by clinicians for the assessment of the severity of TI in lupus nephritis patients." (PMID 39963635, 2025). "Moreover, anti-ACE 2 inversely correlated with total protein and albumin after six months of observation in the lupus nephritis group." (PMID 40364208, 2025). "Moreover, anti-PAR 1 inversely correlated with total protein after two years of observation and albumin at baseline, after one month and two years of observation in the lupus nephritis group." (PMID 40364208, 2025). "Therefore, assessing non-albumin proteinuria can offer clinically valuable insights into the management of lupus nephritis." (PMID 39963635, 2025). "Moreover, anti-C3aR antibodies correlated negatively at many time points of observation with albumin and total protein levels in the lupus nephritis group." (PMID 40943842, 2025). "In lupus nephritis, anti‐dsDNA antibody complexes bind to the components of the glomerulus, inducing inflammation and tissue damage, ultimately leading to increased urinary albumin excretion." (PMID 38346802, 2024).
lupus nephritis (continued). "This decline may be attributable to albumin catabolism induced by inflammation, proteinuria in individuals with lupus nephritis, or the extravasation of albumin due to increased capillary permeability." (PMID 38961124, 2024). "Furthermore, the majority (87.5%) had lupus nephritis, 75% had class V lupus nephritis, and 37.5% had nephrotic range proteinuria with low serum albumin levels." (PMID 35428311, 2022). "Lupus nephritis showed the lowest average hemoglobin and serum albumin values." (PMID 34514568, 2022). "Low serum albumin correlates with kidney disease and outcomes in lupus nephritis." (PMID 34940385, 2021). "Hence, the purpose of this study was to determine the relationship between non-albumin proteinuria and the degree of tubulointerstitial inflammation, as this relationship may provide important clinical information for lupus nephritis patients." (PMID 39963635, 2025). "Thus, concurrently monitoring urine albumin and total protein levels may be useful for assessing the severity of TI and predicting long-term renal prognosis in patients with lupus nephritis." (PMID 39963635, 2025). "Albumin and total protein levels appear to be correlated positively with anti-C3aR antibody levels in FSGS and negatively in lupus nephritis." (PMID 40943842, 2025). "Albumin and total protein levels appear to be correlated positively with anti-C3aR antibody levels in FSGS and negatively in lupus nephritis patients." (PMID 40943842, 2025). "This study aimed to evaluate the prognostic value of C-reactive protein-to-lymphocyte ratio (CLR) in lupus nephritis (LN), and compare its utility with neutrophil-to-lymphocyte ratio (NLR) and fibrinogen-to-albumin ratio (FAR)." (PMID 40988967, 2025). "Mouse kidney function was evaluated by examining complement component 3 (C3) deposition, urinary albumin-to-creatinine ratio (ACR), and lupus nephritis (LN) activity and chronicity." (PMID 36613807, 2022). "The lupus nephritis group’s anti-C3aR antibody level showed a negative correlation with albumin and total protein at several time points of observation." (PMID 40943842, 2025). "Current guidelines do not yet support the routine use of urine albumin-to-creatinine ratio (uACR) for lupus nephritis monitoring, although they recommend serial urine protein-to-creatinine ratio (uPCR) measures in the follow-up of lupus nephritis patients." (PMID 39963635, 2025). "In our meta-analysis, we found that MSC treatment resulted in lower levels of ds-DNA, ANA, Scr, BUN, proteinuria, and renal sclerosis score in lupus nephritis for mice, and MSC treatment could get a higher level of albumin." (PMID 32019582, 2020). "Our study confirmed that MSC treatment in an animal model for lupus nephritis in the studies included in the meta-analysis resulted in lower levels of ds-DNA, ANA, Scr, BUN, proteinuria, and renal sclerosis score, and MSC treatment could get higher levels of albumin." (PMID 32019582, 2020).